CCAR1 (cell division cycle and apoptosis regulator 1)
Diseases named in the same sentence as CCAR1 in open-access papers (continued):
Sharing a sentence is not in itself a finding about the gene and the disease.
cancer (continued). "Collectively, our findings reveal that DCLK1 promotes 5‐fluorouracil resistance in CRC by CCAR1/β‐catenin pathway‐mediated cancer stemness, and suggest that targeting DCLK1 might be a promising method to eliminate cancer stem cells for overcoming 5‐fluorouracil resistance in CRC." (PMID 35522902, 2022). "Furthermore recent work in human cancer cell lines also demonstrates that CCAR1 is involved in Wnt/β-catenin pathway, co-operating with β-catenin and playing an important role in the activation of its target genes, therefore affecting cell growth and proliferation." (PMID 22905258, 2012). "SRSF5 is reported to promote cancer development and progression by regulating the splicing of multiple genes, including ETS1, METTL14, Mcl-1, Cyclin L2, and CCAR1." (PMID 38263157, 2024). "CCAR1 was increased in TCGA HCC samples and was positively correlated with tumor grade, individual cancer stages and nodal metastasis status." (PMID 36932387, 2023). "The remaining 26% either had anti-CCAR1 or anti-SOX5 in isolation, and only 1 of these patients (2% of the group with cancer) had them in combination with another antibody." (PMID 35040440, 2022). "In addition, the negative cancer association with anti-CCAR1 autoantibodies persisted even after controlling for potential confounders (age and biological sex) in multivariable analyses (Johns Hopkins OR 0.13 [95% CI 0.029–0.58], P = 0.008; Stanford OR 0.24 [95% CI 0.06–0.99], P = 0.049)." (PMID 35040440, 2022). "Many of the validated genes bound by ZNF322A such as HMGN5, GATA6, CCAR1 and ELK4, were found to be involved in tumorigenesis in other cancers, further supporting the oncogenic role of ZNF322A." (PMID 30258097, 2019). "When they removed CCAR1 from the cells, they found that the genes targeted by Wnt were not properly activated, and the cancer cells did not grow as they should." (PMID 40978202, 2025). "Cancer rates in anti-CCAR1 positive anti-TIF1γ autoantibody positive patients were also significantly lower than in anti-CCAR1 negative anti-TIF1γ positive patients in both tested cohorts from the USA." (PMID 39514366, 2024). "Although the pro-oncogene role of PDIA5 in cancers has been reported previously, our study revealed another regulatory effect that PDIA5 plays in GBM cells, through the promotion of the expression of the protein CCAR1." (PMID 39247813, 2024). "Cancers that emerged were more likely to be localized (89% of anti-CCAR1–positive cancers presenting at stage 0 or 1 compared with 42% of patients without anti-CCAR1 antibodies, P = 0.02)." (PMID 35040440, 2022). "Patients positive for anti-CCAR1 antibodies were diagnosed with cancer significantly later compared with anti-CCAR1–negative patients (median time from DM onset 4.3 vs. 0.85 years, respectively; P = 0.006)." (PMID 35040440, 2022). "The anti-POLR3A–positive/anti-CCAR1–positive patient had no detected cancer, and it is noteworthy that levels of anti-CCAR1 antibodies were very low in this serum." (PMID 35040440, 2022). "Western blot analysis validated the interaction of known and novel binding partners with Kpnβ1 and revealed enriched interactions between Kpnβ1 and select proteins in cancer cells, including proteins involved in cancer development, such as Kpnα2, Ran, CRM1, CCAR1 and FUBP1." (PMID 36418423, 2022). "The increased interaction of CCAR1 and FUBP1 with Kpnβ1 in cancer cells confirms the mass spectrometry data and suggests that cancer cells may display an increased reliance on CCAR1 and FUBP1 nuclear function." (PMID 36418423, 2022). "Enrichment of anti-CCAR1 autoantibodies in 2 independent cohorts of anti–TIF1-γ–positive DM patients without cancer." (PMID 35040440, 2022). "Considering that our results had proved that DCLK1 promoted cancer stemness, and DCLK1 positively regulated β‐catenin signalling via CCAR1, we speculated that DCLK1 maintained cancer stemness through β‐catenin signalling." (PMID 35522902, 2022).
cancer (continued). "(b) While anti-CCAR1 antibodies in isolation were enriched in patients without cancer, anti-SOX5 autoantibodies in isolation did not have a similar association." (PMID 35040440, 2022). "Mutations in other genes that may be functionally relevant were noted, especially the recently reported high confidence cancer drivers FOXA1 and CCAR1." (PMID 24823478, 2014). "Similarly, for the time analysis in anti-CCAR1–positive vs. –negative patients, the median time of cancer diagnosis from DM onset was 4.3 vs. 0.74 years, respectively; P = 0.002)." (PMID 35040440, 2022). "Furthermore, 89% of anti–TIF1-γ–positive patients with anti-CCAR1 antibodies were diagnosed at stage 0 or 1, which contrasts with 42% of anti–TIF1-γ–positive DM patients without anti-CCAR1 antibodies, who largely presented with more advanced cancers." (PMID 35040440, 2022). "It is possible that use of additional cell lines derived from a range of cancers relevant to the DM disease spectrum as antigen sources may be helpful to discover additional novel autoantigens in this anti-CCAR1 antibody–negative group." (PMID 35040440, 2022). "Interestingly, there are other anti–TIF1-γ–positive/anti-CCAR1–negative DM patients who behave similarly to anti-CCAR1–positive patients (that is, no cancer, or delayed cancer emergence); the size of this population is at least equal to the anti-CCAR1–positive group." (PMID 35040440, 2022). "The finding that anti-CCAR1 antibodies are enriched in patients in whom a cancer never emerges, or emerges after a time delay, prompted us to test whether this observation holds for the other autoantibody specificities identified within the anti–TIF1-γ–positive population." (PMID 35040440, 2022).
tumor (20 papers, 2013 to 2025). "Mechanistically, STK33 phosphorylates and stabilizes CCAR1, which promotes tumor growth and metastasis, thereby driving tumor progression." (PMID 40908551, 2025). "Mechanistically, STK33 phosphorylates and increases the CCAR1 stability, thereby stimulating tumor progression." (PMID 40908551, 2025). "The role of CCAR1 in tumor cell migration, invasion, and proliferation has been validated in various tumors, but its functional effects in GBM cells have not been studied." (PMID 39247813, 2024). "Interactions with pro-oncogenic proteins such as CCAR1 suggested further tumor-promoting functions of PRAME in HCC." (PMID 37173882, 2023). "Here, through a screen of SRSF family, we identified SRSF5 as a glucose-inducible protein that promotes tumor cell growth via AS of CCAR1, a master of cell cycle arrest and apoptosis." (PMID 29942010, 2018). "Here, the authors screened for SR proteins and identified SRSF5 stability is enhanced in response to glucose elevation to promote alternative splicing of CCAR1 which facilitates tumor growth." (PMID 29942010, 2018). "It is likely that a context-dependent tyrosine phosphorylation of CARP-1/CCAR1 plays an important role in signaling for tumor growth or apoptosis, and a thorough functional characterization is needed for further understanding of the mechanism(s) involved." (PMID 25894788, 2015). "CCAR1, a transcriptional co-regulator, favors tumor cell proliferation and migration." (PMID 37173882, 2023). "It has been shown that circRIMS1 might enhance tumor growth, migration, as well as invasion through the miR-433-3p/CCAR1 regulatory axis." (PMID 37917782, 2023). "In addition, IHC analysis confirmed that DCLK1 inhibitor decreased the protein expression of DCLK1 and CCAR1 in subcutaneous tumour in both of DCLK1‐overexpressing and the control groups." (PMID 35522902, 2022). "WA caused tumor growth inhibition, involving direct apoptosis, the increase in pro-apoptotic proteins (p38 stress-activated caspase-3, elevated Bax, PARP cleavage, stimulated expression of CARP1/CCAR1), and blockage in the chymotryptic activity of proteasome." (PMID 34361048, 2021). "Tumor volume and width were measured found that, control group has a fast growing tumor size of 800 mm3 whereas CCAR1-shRNA groups has a relatively slow growing and smaller tumor size of 200 mm3, exerting 75% reduction of tumor size in CCAR 1-shRNA group in comparison control group." (PMID 29861465, 2018). "Furthermore, immunohistochemical analysis of tumor tissues dissected from these mice revealed that, compared to the control group, the si‐circTUBD1 group exhibited decreased E‐cadherin expression and increased N‐cadherin, CCAR1, Ki67, and hnRNPK expression." (PMID 40130381, 2025). "PNA-A15 treatment upregulated A-T repeat-containing genes that act as tumour suppressor genes, such as BAHD1, CCAR1, EGR1, and SLC5A11." (PMID 34059086, 2021). "In light of that the pTNM stage system integrates the clinical significance of the tumor, lymph node and distant metastasis, only pTNM stage, CEA, CA19-9, CREB1, CCAR1 and JNK1 were incorporated into the multivariate analyses." (PMID 30523220, 2018). "SRSF5 promotes the alternative splicing of CCAR1 to produce CCAR1S proteins, which promote tumor growth by enhancing glucose consumption and acetyl-CoA production." (PMID 29942010, 2018). "CCAR1 was relative to tumor depth, distant metastasis and pTNM stage, but not to age, gender, tumor location, tumor size, histological grade, lymph node invasion, CEA, CA125 or CA19-9." (PMID 30523220, 2018). "Univariate analysis revealed that tumor depth, lymph node invasion, distant metastasis, pTNM stage, CEA, CA19-9, CREB1, CCAR1 and JNK1 may act as potential prognosticators." (PMID 30523220, 2018). "Our study also demonstrated that CCAR1 is overexpressed in CRC compared with normal mucosa; is correlative to tumor depth, distant metastasis and pTNM stage; and could be an independent prognosticator." (PMID 30523220, 2018).
tumor (continued). "Immunohistochemistry analysis using anti-CCAR1 antibody confirmed that CCAR1 expression was much weaker in tumor specimens derived from LNCaP-LUC/shCCAR1 grown in mice when compared with LNCaP-LUC/shNS tumors, indicating that CCAR1 depletion was maintained during the tumor formation in mice." (PMID 23887938, 2013). "Lentivirus based Sh-CCAR1 for targeting CCAR 1 and scrambled shRNA as a negative control were prepared to explore the tumor regression capability." (PMID 29861465, 2018).
cardiovascular disease (1 paper, 2018). "However, neither myocardial miR-1254 nor myocardial CCAR1 have been associated with cardiovascular disease." (PMID 30310086, 2018).
CCAR1 also shares sentences with these, for which no sentence is quoted: autoimmune disease (1 paper); bone disorder (1); depression (1); head and neck cancer (1); infertile (1); lymphoma (1); mastitis (1); melanoma (1); scleroderma (1); thyroid adenocarcinoma (1).